IL6 (interleukin 6)
Diseases named in the same sentence as IL6 in open-access papers (continued):
Sharing a sentence is not in itself a finding about the gene and the disease.
Insulin resistance (continued). "In contrast, VAT, situated around internal organs, displays higher lipolytic activity and greater secretion of pro-inflammatory adipokines such as tumor necrosis factor-alpha (TNF-α) and interleukin-6 (IL-6), contributing to insulin resistance and an increased risk of cardiometabolic diseases." (PMID 40491594, 2025). "Interestingly, this IL-6 variant was also found among European and Asian populations yielding similar associations with insulin resistance and obesity." (PMID 40745234, 2025). "Among circulating proinflammatory markers, C-reactive protein (CRP) and interleukin-6 (IL-6) have been extensively studied and are consistently associated with insulin resistance, endothelial dysfunction, and increased risk of cardiovascular events and mortality in T2D." (PMID 40629349, 2025). "Additionally, a high TyG index is associated with chronic inflammation, as insulin resistance induces adipose tissue to secrete pro-inflammatory cytokines, including interleukin-6 and tumor necrosis factor-α." (PMID 40606022, 2025). "Elevated levels of IL-6 are associated with insulin resistance accelerating muscle wasting." (PMID 40357398, 2025). "IL-6 has also been implicated in insulin resistance in several studies." (PMID 40431655, 2025). "Similarly, TNF-α, a multifunctional pro-inflammatory cytokine produced by adipose tissue, and IL-6, another major pro-inflammatory marker, are linked to various health implications including insulin resistance, neurodegeneration, and cancer." (PMID 38999799, 2024). "Notably, these pro-inflammatory factors, such as tumor necrosis factor-α and interleukin-6, were associated with an increased risk of insulin resistance and pancreatic β-cell dysfunction." (PMID 39301319, 2024). "Further, direct cancer effects, such as cancer cachexia is associated with increased insulin resistance and impaired glucose tolerance, and cachexia-associated cytokines, such as tumor necrosis factor and interleukin- 6 are associated with the development of insulin resistance." (PMID 39020360, 2024). "A disorder in this tissue triggers reduced production of adipocytokines, such as adiponectin, and upregulation of the expression of leptin, tumor necrosis factor-α (TNF-α), and interleukin-6 (IL-6), promoting insulin resistance in association with increased visceral adiposity." (PMID 39273464, 2024). "In turn, pro-inflammatory cytokines (TNF-α and IL-6) have the ability to induce the expression of resistin, which is directly related to insulin resistance and is associated with the activation of inflammatory processes through a pathway dependent on nuclear factor κB (NF-κB)." (PMID 39201576, 2024). "For NAFLD, hepatic adipose tissue may facilitate the secretion of some inflammatory cytokines (like tumor necrosis factor‐α and interleukin 6), reduce adiponectin levels, and then cause insulin resistance." (PMID 37840448, 2024). "Excess visceral fat becomes dysfunctional and releases adipokines and inflammatory cytokines, such as tumor necrosis factor-alpha (TNF-α) and interleukin-6 (IL-6), which cause chronic low-grade inflammation and insulin resistance-key characteristics of type 2 diabetes." (PMID 39650923, 2024). "Both processes are the result of adipocyte multiplication through processes such as adipogenesis, increased accumulation of triglycerides in the cytoplasm, and expression of lipogenic enzymes and adipokines, such as IL-6, which are associated with the development of insulin resistance." (PMID 39116155, 2024). "Interestingly, six of the cytokines elevated in 3n mice that were attenuated with the Ch+ diet (IL-1α, IL-1β, IFN-γ, TNF-α, IL-3, and IL-6) have been associated with the development of insulin resistance in T2D." (PMID 39683562, 2024).
Insulin resistance (continued). "Adipocyte cell size has been shown to be an independent predictor of insulin resistance and risk for type 2 diabetes, which was associated with the expression and secretion of important inflammatory molecules (such as TNFα and IL-6), further supporting the proinflammatory state." (PMID 38347470, 2024). "Juicer Broccoli reduces the levels of IL-1β and IL-6 in cells, which helps to alleviate the decrease of insulin secretion and insulin resistance caused by T2DM, improve the disorder of glucose metabolism, reduce inflammatory response and cardiovascular disease risk." (PMID 38254574, 2024). "IL-6 is causally involved in the development of insulin resistance in type 2 diabetes mellitus." (PMID 39597886, 2024). "Although these findings have been reported in adipose tissue, it may explain that increased expression of IL6 mRNA is a sequence of hyperinsulinemia associated with insulin resistance." (PMID 38667300, 2024). "In terms of body weight regulation, IL-6 exhibits a biphasic effect, where acute elevation of IL-6 levels decreases food intake and increases energy expenditure, while chronic elevation of IL-6 levels is associated with increased body weight and insulin resistance." (PMID 37631003, 2023). "Whereas IL-6 deficient mice developed insulin resistance and liver inflammation." (PMID 37426418, 2023). "Cytokines associated with blood sugar control include TNF-α, IL-6, and IL-10, which may have insulin receptor substrates (IRSs) that are converted to serine, which leads to insulin resistance." (PMID 38098816, 2023). "Higher levels of IL-6 and the pro-oxidant malondialdehyde may cause insulin resistance and metabolic disorders in subjects with MS." (PMID 36767947, 2023). "Excess visceral adiposity is associated with altered secretion of bioactive peptides like adiponectin, leptin, interleukin-6, and tumor necrosis factor-α, predisposing to inappropriate inflammatory responses, insulin resistance, increased sympathetic activity and RAAS activation." (PMID 36973671, 2023). "IL-6 was found to enhance insulin secretion in pancreatic islets and the associated hyperinsulinemia, suggesting that IL-6 plays a role in the pathogenesis insulin resistance." (PMID 37996879, 2023). "Studies have shown that PCOS is associated with increased levels of IL-6 that may contribute to insulin resistance." (PMID 37062827, 2023). "Studies have shown that adipose tissue plays an important role as a pro-inflammatory factor in the pathogenesis of PCOS, and the release of tumor necrosis factor alfa (TNF-α) and interleukin-6 (IL-6) from macrophages is associated with the induction of insulin resistance." (PMID 37588599, 2023). "NAFLD is the hepatic manifestation of multiple organ cross-talk due to shared mechanisms, including insulin resistance and chronic inflammation factors such as tumor necrosis factor-alpha and interleukin-6, which contribute to increased CVD events and risk of cardiovascular mortality." (PMID 36837575, 2023). "Some studies have also suggested that low SMD is associated with disease severity, which might be a result of insulin resistance, proinflammatory mediators (such as IL‐6 and TNF‐α), vitamin D deficiency and metabolic acidosis." (PMID 37722854, 2023). "Furthermore, IL-6 has been implicated in insulin resistance through the activation of JNK 1/2, the accumulation of suppressor of cytokine signaling 3 mRNA, and increased protein tyrosine phosphatase 1B activity." (PMID 37511225, 2023). "The mechanism involved is not fully understood but includes cytokine-driven hypermetabolism produced by TNF, IL-1β, and IL-6 (associated with resting energy expenditure and sarcopenia in RA patients), as well as the limitation of physical activity and insulin resistance." (PMID 38069224, 2023).
Insulin resistance (continued). "Proinflammatory cytokines such as tumor-necrosis factor α (TNF-α) and interleukin-6 (IL-6) not only involved in the pathogenesis of hypertension, but also interfered with the insulin signaling pathways which were associated with insulin resistance and diabetes mellitus." (PMID 37139334, 2023). "The increased risk of developing DM may be due to an inflammatory condition associated with RA, with the over-activation of TNFα and IL-6 pathways contributing to an increase in insulin resistance and causing DM." (PMID 36983150, 2023). "IL-6 causes insulin resistance by impairing the phosphorylation of the insulin receptor." (PMID 37139450, 2023). "Circulating IL-6 contributes to the development of atherosclerosis and insulin resistance, the latter being caused by IL-6-induced impairment of the phosphorylation of insulin receptor and insulin receptor substrate-1 by inducing the expression of SOCS-3, a potential inhibitor of insulin signaling." (PMID 35276970, 2022). "In addition, the chronic inflammation of adipose tissue caused by hyperinsulinemia and insulin resistance in obese individuals promotes the secretion of proinflammatory cytokines, such as tumor necrosis factor alpha (TNFα) and interleukin 6 (IL-6)." (PMID 35159342, 2022). "Importantly, our study identified potential links between variation in microbiota composition and associations with insulin resistance, IL‐6, and LPS levels in serum." (PMID 36348812, 2022). "For example, functional deficiency of IL-6 may lead to atherosclerotic lipid conditions and insulin resistance." (PMID 35655218, 2022). "Likewise, it has been reported that IL-6 has a modulating effect on the immune system and is attributed to a mediating role in metabolic processes linked to insulin resistance due to increased sensitivity." (PMID 35739973, 2022). "Also, a study (2015) reported that lipid accumulation in the liver stimulates the secretion of pro-inflammatory factors (TNF-ɑ, IL-6), thus reducing insulin signaling, which ultimately causes more lipid accumulation and insulin resistance." (PMID 36159326, 2022). "Insulin resistance is a hallmark of the metabolic syndrome associated with obesity, TNF-α, IL-6, adiponectin, resistin, and free fatty acids, all of which are contained in visceral fat, may have a role in the development of insulin resistance." (PMID 35159388, 2022). "Both TNF-α and IL-6 have been suggested to be associated with insulin resistance in T2DM subjects." (PMID 35083338, 2022). "STAT3 is associated with IL-6-induced insulin resistance in human skeletal muscle." (PMID 36159557, 2022). "A longitudinal study that investigated thebidirectional relationship between inflammation and insulin resistance showed that baseline levels of hsCRP and IL-6 (interleukin-6) were positively linked with consequent elevations in fasting insulin, HOMA-IR, and beta-cell function." (PMID 37654824, 2022). "Both in vitro and in vivo studies have reported the regulation of PAI-1, SAA, and CRP expression to be closely influenced by the pro-inflammatory cytokines, TNF-α, IL-1β and IL-6, as well as hormones such as GCs which are also associated with insulin resistance and T2D." (PMID 35883605, 2022). "In addition, lean NAFLD is associated with lower levels of proinflammatory cytokines (e.g., interleukin 6 and tumor necrosis factor alpha), which are known as a risk factors for cardiovascular disease, metabolic syndrome, and insulin resistance." (PMID 36198747, 2022). "IL-6 downregulates insulin signaling and causes insulin resistance in adipocytes." (PMID 36339572, 2022). "Increased IL-6 levels are associated with BMI and insulin resistance." (PMID 33584134, 2021). "It is well known that IL-6 is one of the typical cytokines associated with insulin resistance." (PMID 34574191, 2021). "Furthermore, the C-174C genotype of the IL-6 gene is associated with insulin resistance in normoglycemic individuals." (PMID 34579020, 2021).
Insulin resistance (continued). "In this study, we focused on the effects of CCL4 inhibition on the levels of TNF-α and IL-6, which may be related to the root causes of insulin resistance in type 2 diabetes." (PMID 33968046, 2021). "Inflammatory cytokines such as IL-6 and TNFα can also cause insulin resistance, apoptosis, and dysfunction of mitochondria, which are involved in energy production, excessive production of reactive oxygen species, and the acceleration of muscle protein breakdown to eventually result in sarcopenia." (PMID 34575208, 2021). "Previous investigations have revealed that proinflammatory cytokines such as TNF-α and IL-6 could impair insulin signaling, which may cause insulin resistance." (PMID 34371867, 2021). "Consequently, obese patients have increased IL-6 values, which results in an increased risk of cardiovascular diseases, insulin resistance, and diabetes mellitus." (PMID 34683106, 2021). "IL-6 was found to be overexpressed in the adipose tissue of obese individuals, which may cause insulin resistance." (PMID 34831450, 2021). "Interleukin-6 was traditionally classified as a pro-inflammatory cytokine with its elevation being commonly associated with systemic inflammation and insulin resistance; however, more recently its anti-inflammatory properties (particularly during exercise conditions) have also been highlighted." (PMID 35211515, 2021). "CRP and IL-6 are also implicated in pathogenesis of insulin resistance and may exaggerate the effects of insulin resistance on psychosis risk in young adults." (PMID 33711016, 2021). "However, adipose tissues have been implicated in the release of inflammatory mediators such as interleukin-6 and tumor necrosis factor α, and also linked to the cause of insulin resistance." (PMID 34421824, 2021). "In the present study, the KO mice had abdominal fat accumulation, which indicated that IL-6 might be one of the factors that make abdominal adipose tissue a high-risk factor for the development of insulin resistance." (PMID 33060792, 2020). "IL-6, in the pathogenesis of DN, is associated with insulin resistance." (PMID 33178322, 2020). "Because increased interleukin-6 cytokine is considered to be associated with insulin resistance and beta cell dysfunction, it could be a risk factor for T2DM." (PMID 32781787, 2020). "Moreover, the secretion of interleukin (IL)-6 from adipose tissue causes hepatic insulin resistance." (PMID 33292449, 2020). "The data of the current study demonstrate an increase in CRP and IL-6 levels in obese subjects, which could highlight the marked inflammatory process that is linked to insulin resistance in obese subjects." (PMID 32708841, 2020). "In addition, high levels of serum TNF-α and IL-6 have shown to be linked to obesity and insulin resistance which are key players in metabolic syndrome." (PMID 33344519, 2020). "TNFα and IL6, which are both positively associated with insulin resistance (Hotamisligil, Shargill, & Spiegelman, 1993; Pickup, Mattock, Chusney, & Burt, 1997), were increased in plasma of HFD‐fed Park2 KO mice, inconsistent with the observed phenotype with regards to insulin sensitivity." (PMID 31724300, 2019). "In this sense, IL-6 is a cytokine that has been associated with insulin resistance." (PMID 31370223, 2019). "Thus, acquired insulin resistance and glucose intolerance are associated with chronic inflammation, the pro-inflammatory cytokine being IL-6 the main link between both processes." (PMID 31064136, 2019). "To date, only one longitudinal study has examined the bidirectional relationship between inflammation and insulin resistance and showed that baseline levels of hsCRP and interleukin-6 were positively associated with subsequent increases in fasting insulin, HOMA-IR, and beta-cell function." (PMID 31443647, 2019). "IL-6 is also a biomarker of insulin resistance and cardiovascular diseases risk." (PMID 31921154, 2019).
Insulin resistance (continued). "Insulin resistance is also caused by inflammatory mediators such as interleukin‐6 (IL‐6)." (PMID 31289664, 2019). "Moreover, IL-6, which is highly expressed in VAT, is directly related to the cause of liver insulin resistance, and an increase in the IL-6 concentration is a predictor of the development of type II diabetes." (PMID 31357412, 2019). "In addition, it has been demonstrated that circulating IL-6 is associated with body fat and insulin resistance." (PMID 30558209, 2018). "Its quantitative release from adipose tissue results in a subclinical and systemic elevation of IL-6 plasma levels with increasing body fat content, which may be implicated in the proinflammatory state leading to insulin resistance." (PMID 29849618, 2018). "IL-1β, and IL-6, C-reactive protein also causes insulin resistance." (PMID 30246011, 2018). "Moreover, a murine model has shown that elevated IL-6 level is associated with several diseases which include cardiovascular events, atherosclerosis, and hypertension and chronic IL-6 exposure causes hyperglycemia associated with insulin resistance." (PMID 30425746, 2018). "Mechanistically, extracellular HCV core protein with substitution at position 70 was found to enhance IL-6 production and reduce adiponectin production from visceral adipose tissue, which can cause insulin resistance, hepatic steatosis, and ultimately development of HCC." (PMID 29577052, 2018). "Among RA-related risk factors, proinflammatory cytokines (TNF-α, IL-6), oxidative stress, an increase of leptin and resistin (proatherogenic hormones) and the decrease of adiponectin (antiatherogenic hormone), and insulin resistance play the most important role in accelerated atherogenesis." (PMID 29200598, 2017). "An example is IL6, upregulation of which is strongly associated with insulin-resistance and NAFLD." (PMID 29121861, 2017). "Insulin resistance has been associated with both serum IL-6 and CRP levels in previous studies, and concomitant improvements (reductions) in these parameters have been observed following exercise training for 12 weeks in obese subjects, whereas TRACP-5a titers remained elevated." (PMID 29100456, 2017). "In addition, IL-6 causes insulin resistance due to the defect in IRS phosphorylation leading to decrease in gluconeogenesis and increased glycogenolysis." (PMID 28505155, 2017). "gingivalis-43-periodontitis-41-TNFα/IL6-inflammatory state-60-insulin resistance-vasodilation shows how periodontal disease could be linked to changes in vasodilation." (PMID 27846870, 2016). "After adjustment for age, waist circumference, resistin, CRP, PAI-1, adiponectin and glycated hemoglobin levels, the association of having insulin resistance and higher levels of IL-6 (OR = 1.390, p = 0.005) and MCP-1 (OR = 1.006, p = 0.026) became stronger (model 4)." (PMID 26862350, 2016). "Hepatic IL-6 increases glucose release and causes insulin resistance in the liver." (PMID 28025491, 2016). "Model 3 shows that presence of insulin resistance was positively associated with resistin (OR = 1.017, p = 0.001), IL-6 (OR = 1.393, p = 0.002) and glycated hemoglobin (OR = 3.332, p = 0.036) and negatively associated with age (OR = 0.921, p = 0.024) and PAI-1 levels (OR = 0.981, p = 0.017)." (PMID 26862350, 2016). "Results from group analysis suggested that high IL-6 levels in PCOS were significantly associated with Homeostasis Model Assessment of Insulin Resistance (HOMA2-IR) ratio and total testosterone ratio (T ratio), and was found in both lean and obese women with PCOS." (PMID 26849353, 2016). "The inflammatory mediators, TNFα and IL-6, which are associated with insulin resistance in T2DM, enhanced estrogen production in both normal and breast cancer cells and could be expected to result in the development and proliferation of breast cancer cells." (PMID 25866823, 2015).